PIEZO1 (piezo type mechanosensitive ion channel component 1 (Er blood group))
Diseases named in the same sentence as PIEZO1 in open-access papers (continued):
Sharing a sentence is not in itself a finding about the gene and the disease.
colon cancer (24 papers, 2020 to 2025). "Recently, PIEZO1 was found to be highly expressed in the CD133 + CD44+ colon cancer tissue and associated with patients in the advanced clinical stage." (PMID 40890143, 2025). "Mechanical forces within tumors themselves regulate Piezo1 signaling that affects tumor growth and metastasis; and clinically, upregulation of Piezo1 expression in colon cancer is associated with a poor patient prognosis." (PMID 37781915, 2023). "Piezo1 was activated by Yoda1 that is an effective activator of Piezo1 channel, and highly expressed Piezo1 in HCT-116 and SW-480 cells was in negative association with cell viability; however, silencing Piezo1 suppressed colon cancer cell viability." (PMID 32152662, 2020). "In this study, we provided evidence that Piezo1 was associated with tumor metastasis in colon cancer patients." (PMID 32152662, 2020). "Piezo1 expression has been closely linked to CCSCs and the staging of colon cancer." (PMID 39062518, 2024). "Furthermore, the expression of Piezo1 in colon cancer is significantly higher and associated with a poorer prognosis." (PMID 36837670, 2023). "Transwell and wound-healing assays were performed to investigate whether Piezo1 was in association with colon cancer metastasis." (PMID 32152662, 2020). "Meanwhile, overexpression of PIEZO1 can promote the migration and motility of colon cancer cells via a potential mechanism related to the PIEZO1‐MCU‐HIF‐1α‐VEGF axis." (PMID 38494915, 2024). "Mutations in KIAA1217, POLD1, PIEZO1, NBEAL2, DDX17, and PARP14 were significantly more prevalent in patients with colon cancer and PRShigh than in those with PRSlow." (PMID 38577604, 2024). "An interesting observation was that Piezo1 overexpression enhanced colon cancer cell survival, migration, and metastasis capabilities." (PMID 39062518, 2024). "Overall, Piezo1/2 has significant implications for colon cancer treatment, specifically the precise targeting of HIF and VEGF." (PMID 39062518, 2024). "Piezo1high/CD133+CD44+ colon tumors are associated with advanced clinical stage, suggesting that the presence of Piezo1high/CD133+CD44+ CCSCs is a potential prognostic marker, and Piezo1 is a promising target for the selective elimination of CCSCs." (PMID 37306789, 2023). "Taken together, Piezo1 expression is closely related to CCSCs and the stage of colon cancer patients." (PMID 37306789, 2023). "In line with this, we detected higher expression of Piezo1 in the CD133+CD44+ CCSC fraction isolated from different colon cancer cell lines." (PMID 37306789, 2023). "We found that Piezo1 was highly expressed in the CD133+CD44+ colon cancer tissues, and patients with Piezo1high/CD133+CD44+ tumors were usually in the advanced stage." (PMID 37306789, 2023). "Consistent with the in-situ results, Piezo1 was overexpressed in the CD133+CD44+ fraction of multiple colon cancer cell lines, including HCT-116, HCT-8, SW480 and HT-29." (PMID 37306789, 2023). "To assess the relationship between Piezo1 and CCSCs in colon cancer patients, we evaluated the expression of Piezo1, CD133 and CD44 in the tumor tissues." (PMID 37306789, 2023). "In this study, we found that Piezo1 was highly expressed in CD133+/CD44+ colon cancer tissues, and the Piezo1high/CD133+CD44+ population was associated with the clinical stage." (PMID 37306789, 2023). "At the molecular level, Piezo1 promotes colon cancer cell migration and invasion via MCU/HIF-1α/VEGF signaling." (PMID 37306789, 2023). "In this study, we found that Piezo1 knockdown impaired the stemness of CCSCs in vitro and in vivo, which suggests that Piezo1 is a potential therapeutic target for colon cancer." (PMID 37306789, 2023). "Taken together, Piezo1 is involved in the stage of colon cancer and is a promising therapeutic target." (PMID 37306789, 2023). "In colon cancer cells, Yoda1 application increases cell migration, and the silencing of Piezo1 shows the opposite effect." (PMID 35884459, 2022).
colon cancer (continued). "Next, we studied the effect of DC-specific Piezo1 deletion on T cell differentiation in MC38 mouse colon cancer." (PMID 35993548, 2022). "Similar results were obtained by ultrasonic-activated Piezo1 in pancreatic cancer cells and inducing Piezo1 expression using Yoda1 in colon cancer, which elevated mitochondrial membrane potential and induced cell death." (PMID 36230880, 2022). "The overexpression of Piezo1 promotes the migration of colon cancer cells and downregulates the mitochondrial membrane potential." (PMID 36615408, 2022). "The upregulated expressions of Piezo1 and HIF-1α are closely linked to poor prognosis in patients with colon cancer." (PMID 36615408, 2022). "Immunohistochemical analysis of samples from patients with colon cancer revealed that Piezo1 expression was upregulated in cancer colon tissues and cells, compared with that in adjoining normal tissues." (PMID 36060694, 2022). "The results indicate that the signaling axis of Piezo1-MCU-HIF-1α-VEGF mediates the metastasis of colon cancer cells." (PMID 36615408, 2022). "For example, in a previous study of colon cancer, Piezo1 knockdown significantly reduced the viability of HCT116 and SW480 cells." (PMID 34831037, 2021). "In one study, Piezo1 promoted VEGF expression in colon cancer, with Piezo1 expression elevated in colon cancer tissue and acting as a prognostic factor for patients." (PMID 34831037, 2021). "Despite extensive functional studies, the potential role of Piezo1 in colon cancer metastasis remains largely unclear." (PMID 32152662, 2020). "This study aimed to explore the function of the mechanically activated ion-channel Piezo1 in the colon cancer metastasis and its potential regulatory mechanism." (PMID 32152662, 2020). "The expression of Piezo1 was elevated in colon cancer tissues, and the expression of Piezo1 was a prognostic factor for colon cancer patients." (PMID 32152662, 2020). "At the mRNA and protein levels, Piezo1 expression was higher in colon cancer tissues than in the adjacent normal colon tissues." (PMID 32152662, 2020). "Taken together, Piezo1 is involved in colon cancer cell viability, apoptosis, migration, and metastasis." (PMID 32152662, 2020). "Combining with previous research, our findings confirmed that Piezo1 is involved in colon cancer cell metastasis and proposed a potential Piezo1-mediated molecular signaling pathway, Piezo1-MCU-HIF-1α-VEGF." (PMID 32152662, 2020). "With regard to the mechanism by which Piezo1 is up-regulated in colon cancer, we found that Piezo1 mRNA was significantly increased." (PMID 32152662, 2020). "And, PIEZO1 drives colon cancer cell growth, migration, and metastasis." (PMID 40977743, 2025). "Notably, high Piezo1 expression is strongly correlated with poorer prognosis in patients with colon cancer." (PMID 39062518, 2024). "Thus, Piezo1 promotes colon cancer development by regulating the Piezo1–MCU–HIF-1α–VEGF signaling pathway." (PMID 39062518, 2024). "Given that the role of CCSCs in the relapse and chemo-resistance of colon tumor cells, and the critical role of Piezo1 in cancer development, we hypothesized that Piezo1 may regulate the stemness and tumorigenic potential of CCSCs." (PMID 37306789, 2023). "Knockdown of Piezo1 channels by siRNA blocked the effects of mechanical stress to promote tumor malignancy and cancer metastasis in human colon cancer cell lines (HCT-116, SW-480) and similarly promoted gastric cancer in a xenograft model of human gastric tumors in BALB/c nude mice." (PMID 37781915, 2023). "Therefore, Piezo1 is a potential target for the selective elimination of CCSCs in colon cancer treatment." (PMID 37306789, 2023). "High levels of Piezo1 can reduce the survival rate of colon cancer patients." (PMID 36060694, 2022).
colon cancer (continued). "Piezo1 is involved in colon cancer cell metastasis; its expression is significantly elevated in prostate cancer cell lines and human prostate cancer tissues, and downregulation of Piezo1 significantly inhibits prostate cancer cell survival, proliferation, and migration." (PMID 36230965, 2022). "However, the implications of Piezo1 in lung cancer contradict the other reported tumors, such as colon cancer, gastric cancer, and hepatocellular carcinoma." (PMID 36230880, 2022). "In the hypoxic environment of colon cancer, highly expressed Piezo1 activates the MCU." (PMID 36187789, 2022). "Some studies have confirmed that Piezo1 could promote malignant biological behavior involving viability, migration, and metastasis of colon cancer cells." (PMID 35991548, 2022). "Therefore Piezo1 and MCU are likely to play a role in colon cancer cell metastasis through the Piezo1-MCU-HIF-1α-VEGF pathway." (PMID 36187789, 2022). "It has been confirmed that Piezo1 induced the expression of HIF‐1α in colon cancer cells." (PMID 33439514, 2021). "We found that Piezo1 overexpression dissipated the MMP compared to Piezo1 knockdown, indicating that Piezo1 could mediate colon cancer cell apoptosis." (PMID 32152662, 2020). "Overexpression of Piezo1 promoted colon cancer cell viability, migration, and metastasis." (PMID 32152662, 2020). "In our study, Piezo1 is involved in colon cancer cell metastasis." (PMID 32152662, 2020). "In this study, we found that Piezo1 expression was up-regulated in colon cancer tissues." (PMID 32152662, 2020). "To determine whether Piezo1 participated in the development of colon cancer, we first examined the expression of Piezo1 by immunohistochemistry." (PMID 32152662, 2020). "Furthermore, to evaluate the clinical significance of Piezo1 in colon cancer, the correlation between its expression level and clinical parameters was analyzed." (PMID 32152662, 2020). "Our findings revealed that overexpressed Piezo1 promoted colon cancer cell migration and motility." (PMID 32152662, 2020). "Additionally, Piezo1 may influence the metastasis and prognosis of colon cancer via the Piezo1-MCU-HIF-1α-VEGF axis (Sun YH." (PMID 38690080, 2024). "Furthermore, overexpressed Piezo1 significantly promoted colon cancer cell migration." (PMID 32152662, 2020). "However, our results showed that 100 μM Yoda1 could significantly activate the expression of Piezo1 in the two colon cancer cells, which might reflect the heterogeneity between different cancer cells." (PMID 32152662, 2020). "Thereby, Piezo1 could participate in colon cancer progression by reducing cell viability." (PMID 32152662, 2020). "The role of Piezo1 in colon cancer metastasis remains largely unknown." (PMID 32152662, 2020). "In the present study, we found that Piezo1 expression was high in the CD133+CD44+ CCSC fraction, and the Piezo1high/CD133+CD44+ colon cancer patients were in the advanced clinical stage." (PMID 37306789, 2023). "Contrary to Piezo1, MCU knockdown promoted colon cancer cell viability, migration, motility, and metastasis." (PMID 32152662, 2020). "In colon cancer cells treated with Yoda1, HIF-1α expression was significantly up-regulated, whereas HIF-1α expression was significantly inhibited after silencing Piezo1." (PMID 32152662, 2020). "Second, functional assays were performed to investigate the effects of Piezo1 and MCU on colon cancer cell migration, invasion, and mitochondrial membrane potential." (PMID 32152662, 2020). "First, we examined the expression levels of Piezo1 and mitochondrial calcium uniporter (MCU) both in colon cancer tissues and assessed the prognostic value of Piezo1 and MCU in a colon cancer cohort (n = 110)." (PMID 32152662, 2020). "Compared with low stemness colon cancer stem cell-like cells (CCSCs) and non-CCSCs, Piezo1 is highly expressed in CCSCs with high stemness, and the population with high Piezo1 expression is associated with clinical stage." (PMID 38690080, 2024).
colon cancer (continued). "Piezo1 and MCU were both correlated with poor prognosis of patients with colon cancer." (PMID 32152662, 2020). "Therefore, in our study, we explored the regulatory relationships among Piezo1, MCU, and HIF-1α in colon cancer metastasis." (PMID 32152662, 2020). "Overexpressing Piezo1 and silencing MCU could promote colon cancer cell migration and metastasis, reduce mitochondrial membrane potential, and promote each other’s expression." (PMID 32152662, 2020). "We found that Piezo1 was up-regulated and MCU was down-regulated in colon cancer tissues." (PMID 32152662, 2020). "In the present study, VEGF expression was inhibited after overexpression of Piezo1, suggesting that Piezo1 could mediate VEGF expression, thereby affecting colon cancer cell metastasis." (PMID 32152662, 2020). "It appears that mechanical stress triggers Piezo1 signaling, leading to reduced expression of mitochondrial calcium uniporter, increased expression of HIF-1α and VEGF, and decreased mitochondrial membrane potential production, which promote colon cancer cell metastasis." (PMID 37781915, 2023). "Our results suggest that Piezo1 promotes colon cancer cell viability, migration, and metastasis; furthermore, Piezo1 could be involved in a possible regulatory mechanisms of Piezo1-MCU-HIF-1α-VEGF in colon cancer." (PMID 32152662, 2020). "Moreover, we hypothesized Piezo1-MCU-HIF-1α-VEGF axis, a potential regulatory mechanism in colon cancer metastasis." (PMID 32152662, 2020).
channelopathy (21 papers, 2018 to 2025). Channelopathies are a group of diseases caused by the dysfunction of ion channel subunits or their interacting proteins. "We further demonstrate that changes in endothelial PIP2 levels in different pathological conditions are associated with a Piezo1 channelopathy." (PMID 41433068, 2025). "It was argued that transient Piezo2 channelopathy also means a transient loss of crosstalk between Piezo1 and Piezo2." (PMID 37999426, 2023). "Coarse-grain molecular dynamics simulations suggest that cholesterol and margaric acid interact with PIEZO1 through many of the residues associated with PIEZO1 channelopathies." (PMID 36069933, 2022). "Additionally, we can introduce pathogenic PIEZO1 Gain- or Loss-of-Function mutations in the PIEZO1-HaloTag hiPSCs for human disease modeling of PIEZO1 channelopathies." (PMID 38187535, 2025). "In addition, pathogenic PIEZO1 Gain-of-Function15,18,19 or Loss-of-Function69 mutations can be introduced in the PIEZO1-HaloTag hiPSCs for disease modeling of human PIEZO1 channelopathies." (PMID 40593468, 2025). "The autonomously acquired Piezo2 channelopathy was also suggested to cause impaired cross-frequency coupling between proprioceptive Piezo2 and Piezo1 in peripheral cells through lost Huygens synchronization in a given compartmental micromilieu involving mitochondria and protons." (PMID 40076941, 2025). "This is of particular importance since an increasing number of Piezo1 mutations have been reported and also other channelopathies, e.g., involving the Gardos channel may interact with the non-selective voltage-dependent cation channel/Piezo1." (PMID 30524293, 2018). "Therefore, the current authors propose that impaired crosstalk between somatosensory-terminal Piezo2 and peripheral Piezo1 due to Piezo2 channelopathy could also cause biased regulation of progenitor stem-cell identity." (PMID 37108693, 2023). "This suggests that in the future utilizing proteasomal inhibitors in use in the clinic in combination with a precision medicine-based approach we may be able to rectify the mis-localization and reduced function of Piezo1 channels associated with a subset of Piezo1-channel mediated channelopathies." (PMID 34867393, 2021). "We further observed an upregulation of capillary EC Piezo1 function in different disease mouse models, and importantly, PIP2 corrected this Piezo1 channelopathy and the associated cerebral blood flow (CBF) deficits." (PMID 41433068, 2025). "In summary, these observations demonstrate the effectiveness of PIP2 to correct a CBF deficit in a mouse model of Piezo1 channelopathy." (PMID 41433068, 2025). "In summary, it seems that chronic spinal facet joint Piezo2 channelopathy and the resultant impaired Piezo2-Piezo1 crosstalk will eventually lead to IL-17-induced entheseal Piezo1 upregulation in a feed-forward, low-grade inflammatory manner in AS." (PMID 37895134, 2023). "Moreover, this acquired Piezo2 channelopathy also proposed to impair the crosstalk between Piezo2 and Piezo1 channels in the given compartmental micromilieu and the crosstalk between Piezo2 and Piezo2 channels beyond the given compartments." (PMID 41155507, 2025). "However, it is important to note again that these mechanisms are severely and progressively impaired due to the theorized irreversibility of Piezo2 channelopathy and resultant lost crosstalk between Piezo2 and Piezo1 in the affected compartments of ALS." (PMID 38534336, 2024). "This acquired channelopathy may also mean an impaired crosstalk between Piezo2 and Piezo1 channels within the affected compartment." (PMID 38534336, 2024). "An important consideration is that the impairment of this cross-talk could arise from both directions, from PIEZO1 channelopathy and PIEZO2 channelopathy as well." (PMID 39519393, 2024).